CD4 (CD4 molecule)
Diseases named in the same sentence as CD4 in open-access papers (continued):
Sharing a sentence is not in itself a finding about the gene and the disease.
tumor (continued). "In vivo T cell-intrinsic loss of CDK6 reduces numbers of tumor-infiltrating CD4+ T cells and Tregs without affecting tumor growth." (PMID 34248938, 2021). "However, C5AR1 expression shows a weak (r = 0.2~<0.5) to poor (r < 0.2) correlation with tumor infiltrations of CD4+ T cells, CD4+ T cells, and B cells in various cancer types." (PMID 34439277, 2021). "However, the percentage of effector Treg subsets (CD4+CD25hiFoxp3+) after cryo-thermal therapy was significantly downregulated compared to tumor-bearing control and RFA-treated mice." (PMID 34576115, 2021). "CD4+ T cells provide “help” to cytotoxic CD8+ T cells to support tumor control." (PMID 33809259, 2021). "It is confirmed that the role of CD4+ T cell infiltration is more complex in tumor progression." (PMID 34654443, 2021). "In addition, tumor-infiltrating B cells and tumor-infiltrating CD4 + T cells created three-level structures of lymphoid that was positively correlated with the survival rate of NSCLC." (PMID 34603645, 2021). "However, to confer antitumor specificity to the host, these strategies often require additional treatments such as the corresponding tumor cell lysate vaccinations and/or chemotherapy prior to the administration of allogeneic CD4+ T cells." (PMID 34625113, 2021). "Remarkably, PD-1cKO mice could control tumors as large as 1,500 mm3, and after initial tumor growth, inhibition or complete responses were observed correlating with the progressive deletion of PD-1 expression on CD4 and CD8 T cells." (PMID 34912335, 2021). "ICI therapy can activate T cells, and this may subsequently result in higher IL-2 production by CD4+ T-helper cells in the tumor microenvironment." (PMID 34076745, 2021). "Overexpression of MAGI2-AS3 or knockdown of CTD-3184A7.4 may activate memory resting CD4+ T cells to enhance immune response against tumor cells." (PMID 33665192, 2021). "The ratio of CD8+T cells/CD4+T cells can influence the product regarding tumor eradication." (PMID 34422050, 2021). "We identified a CD4 tumor-infiltrating lymphocyte (TIL) population, defined by high PD-1 and CD39 expression, which contained high proportions of cytokine-producing cells, although the quantity of cytokines produced by these cells was low, evoking an exhausted state." (PMID 33332284, 2021). "An immunosuppressive microenvironment was seen in tumour draining lymph nodes involved by cervical carcinoma compared to lymph nodes free of tumour with higher number of CD4 and CD8 positive Tregs and increased expression of PDL1 and B7-H4, a coinhibitory molecule." (PMID 34640541, 2021). "Collectively the data shows that in tumor infiltrating CD4+ T-cells, DNA methylation might regulate certain gene expression, where hypomethylation of a DMR corresponds with the expression of the corresponding gene and vice versa." (PMID 34012510, 2021). "Moreover, we detected the change of three types of immune cells in the spleen of the tumor-bearing mice, including CD4+ T cells, CD8+ T cells, and CD206+ T macrophages." (PMID 34660289, 2021). "HLA class II on TILs, PD-L1 on TILs, CD4, and FOXP3 were enrolled in the immune risk model, which categorized patients into high-risk and low-risk groups and had better power for predicting the recurrence than tumor stage." (PMID 34362829, 2021). "All above results suggested the cGAS-STING pathway, as a cytosolic DNA-sensing pathway, played the potential contribution of anti-tumor efficiency through mediating the recruitment, activation, and differentiation of CD4+ and CD8+ T cells, especially the CD8+ T cells." (PMID 34956229, 2021). "Disruption of EZH2 activity in Treg cells via either genetic or pharmacologic means led to the acquisition of pro-inflammatory functions in tumor-infiltrating Treg cells, the remodeling the TME and enhanced recruitment and function of CD8+ and CD4+ effector T cells, leading to tumor elimination." (PMID 34930302, 2021).
tumor (continued). "Notably, en-T cells showed a significantly higher ratio of CD25-expressing cells in CTXpre/CD4post than in the CTXpre group, implying that anti-CD4 treatment heightened the tumor reactivity of CD8+ T cells." (PMID 34493727, 2021). "The treatment with CsA or anti-CD4/anti-CD8 completely abolished the anti-tumor effect of AAGL." (PMID 33710817, 2021). "The high-risk group was more significantly associated with tumor-infiltrating immune cells, such as macrophages, neutrophils, and CD8+ T cells, but negatively associated with myeloid dendritic cells and CD4+ T cells, as verified using the Wilcoxon signed-rank test." (PMID 34663340, 2021). "Cytotoxic CD8+ T cells and CD4+ helper T cells could target antigenic tumor cells to suppress tumor progression." (PMID 34395248, 2021). "Furthermore, considering the complexity of the tumor immune microenvironment, the prognostic values of other intratumoral-infiltrating T-cell subgroups, such as CD4+, FOXP3+ T-cells, are needed for further exploring." (PMID 34717647, 2021). "There are a number of subsets of CD4 + T cells that have different functions within the tumor." (PMID 34952631, 2021). "This indicates that the enhanced accumulation of CD8+ and CD4+ T cells in central tumor areas might be regulated through a chemotactic interaction." (PMID 34234274, 2021). "CD4+ T cells primarily mediate anti-tumour immunity by providing help for CD8+ CTL and antibody responses, as well as via secretion of effector cytokines such as interferon-γ (IFNγ) and tumour necrosis factor-α (TNFα), and, under specific contexts, via direct cytotoxicity against tumour cells." (PMID 32457487, 2021). "Interestingly, the use of anti-Gr1 antibody also induces an increase of CD8+ and CD4+ T cells within the tumor, suggesting that VEGF-A reduces the infiltration of cytotoxic T lymphocyte through MDSC." (PMID 34064508, 2021). "In addition, the cytotoxic effector CD4+ T cells, most closely related to Th1 subset, can directly eliminate tumor cells through the MHC class II-dependent manner, which destroy target cells by secreting granzyme B and perforin." (PMID 33791306, 2021). "Three general approaches to targeting CD4+T cells could be considered for CRC therapy: A. Direct inhibition CD4+T cell-derived tumor promoting factors." (PMID 34489941, 2021). "Similar mechanisms could be important for shaping the identity of tumor infiltrating CD4+ T cells within the TME." (PMID 34012510, 2021). "Moreover, our data support recent data which show that the intratumoral selective accumulation of resting memory CD4+ T cells at the expense of memory activated CD4+ T cells denotes a pivotal mechanism to constrain tumor growth." (PMID 34234215, 2021). "High proportions of Tregs among tumor-infiltrating CD4+ T cells were favorable." (PMID 35223866, 2021). "Indeed, tumor-infiltrating CD4+ T cells expressing IL2 were increased after TIGIT blocking monoclonal antibody (mAb) treatment in a head and neck squamous cell carcinoma mouse model." (PMID 34367161, 2021). "It implicates that CD8+ TILs have a prominent role in controlling the progression of disease, with positive impact on overall survival, whereas the high percentage CD4+TILs in the tumour microenvironment may contribute to poor prognosis." (PMID 34150643, 2021). "However, it is important to note that just like the concern with CAR-T cells, there is a challenge with the tumor localization of the injected ex vivo activated CD4+T cells." (PMID 33918403, 2021). "Furthermore, tumor-infiltration levels of immune cells (B cells, CD4+ T cells, CD8+ T cells, neutrophils, macrophages, and dendritic cells) were significantly higher in patients with high IGSF10 expression compared to those with low IGSF10 expression." (PMID 34351868, 2021). "PSGL-1 engagement in the tumor microenvironment may promote CD4+ T cell exhaustion pathways that favor tumor growth." (PMID 33708224, 2021).
tumor (continued). "Comprehensive IHC analyses revealed that TAX2 peptide immune mode of action mostly relies on adaptive immunity, since it does not only increases the number of infiltrating CD4+ T lymphocytes, but also stimulates deeper T-cell infiltration within the tumor mass." (PMID 34638503, 2021). "Furthermore, both CCR7 expression on tiDC2s and expansion of the dLN migratory DC2s were not lost following CD4 depletion, demonstrating that DC2 migration is upstream of CD4+ T cell infiltration to the tumor." (PMID 34283809, 2021). "In LUSC, proportions of CD4+ T cells, B cells, NK cells and uncharacterized cells were significantly higher while that of Macrophages and Endothelial cell were significantly lower in tumor tissues compared with that of normal tissues." (PMID 34923982, 2021). "Besides reducing tumor cell proliferation and inducing apoptosis, colchicine enhances CD4+ and CD8+ T-cell-mediated anti-tumor immunity by promoting dendritic cell maturation and antigen presentation." (PMID 35097027, 2021). "In the context of the tumor microenvironment, CD4+CD25+FOXP3+ Tregs have been extensively studied." (PMID 33802331, 2021). "Although TGFβ expression was not changed with CHK1i+LDHU treatment, this cytokine is strongly expressed in these tumours suggesting that intra-tumourally recruited CD4+ T and NKT cells are converted into FoxP3+ regulatory cells by the high levels of TGFβ in the tumour microenvironment." (PMID 34359633, 2021). "The involvement of immune cells in controlling the growth of LL/2-tdTomato/Luc cells is further confirmed by the lymphocyte depletion studies, which showed that the LL/2-tdTomato/Luc tumor growth in mice depleted of CD4, CD8 or NK cells is similar to the LL/2 tumor growth." (PMID 34411144, 2021). "Thereby, it is reasonable to speculate that in the tumour microenvironment, p73 expression in the CD4 T-cells suppresses Th1 polarisation and promotes Th2 polarisation, M2-like macrophages, and immunosuppressive tumour microenvironment." (PMID 34944027, 2021). "Finally, in PD-1cKO mice with CR, injection of tumor cells resulted in an expansion of the EM CD8+ and CD4+ CM and EM T cells in the lymph nodes at day 3 post-tumor cell challenge." (PMID 34912335, 2021). "Indeed, the addition of redirected MHC II-restricted CD4+ to MHC I-restricted CD8+ T cells was shown to strongly increase tumor regression in a xenograft mouse model." (PMID 34853796, 2021). "These molecules may well function as gatekeepers for the conversion of Tregs into anti-tumour effector CD4+ T cells." (PMID 32457487, 2021). "Similar dissection of cytotoxic CD4+ T cell-dependent anti-tumor activity and how this may synergize with other anti-tumor effectors will be illustrative." (PMID 34910940, 2021). "Besides macrophage activation and NK cell recruitment, tumor infiltration by CD4+ T cells also plays a pivotal role." (PMID 34209192, 2021). "On the other hand, immune checkpoint inhibitors act by removing the inhibitory pathways that block antitumor T cells, and it is well documented that their efficacy is directly proportional to tumor mutational burden, which generates cancer-specific neo-epitopes recognized by CD8+/CD4+ T cells." (PMID 34835287, 2021). "The mechanisms in which Foxp3+ T cells promoted HCC progression might include fostering angiogenesis, decreasing CD8+ T cells, progressively reducing CD4+ CTLs, and boosting the formation of portal vein tumor thrombi (PVTT) and so on." (PMID 34566989, 2021). "Apoptotic cell clearance via efferocytosis polarizes tumor-associated macrophages (TAM) to adopt pro-tumor ‘M2’ wound-healing phenotypes which, by secreting cytokines such as IL-4, IL-10, IL-13 and TGF-β1, further educate Th0 or Th1 CD4 T cells towards a Th2 phenotype." (PMID 34359823, 2021).
tumor (continued). "Further investigation on the tumor immune microenvironment with the IGRPM indicated that low-risk patients had a higher ImmuneScore and possessed a larger amount of activated TICs, such as CD8+ T cells, activated CD4+ memory T cells, and macrophages M1." (PMID 34108992, 2021). "The mechanisms by which HIF-1 suppresses the function of effector T-cells are complex, but include the upregulation of co-inhibitory receptors (e.g., CTLA-4 and LAG-3), the differentiation of CD4+ T-cells into Tregs and the indirect effect of altered tumour cell metabolism." (PMID 33923305, 2021). "An adaptive anti-tumor immune response was evidenced by the slightly decreased percentage of CD4+ helper cells among CD3+ lymphocytes, both in the blood and in the pancreas, but concurrent with a statistically significant increase in the percentage of CD8+ cells in the pancreas." (PMID 33808692, 2021). "By targeting of tumor stroma and subsequent angiogenesis blockade, tumor growth could be inhibited in an IFN-γ–mediated way by CD4+T cells." (PMID 34497832, 2021). "CD4+T cells from non-tumor bearing mice were isolated from splenocytes of 12-week-old C57Bl/6 mice." (PMID 33918403, 2021). "It is attractive to speculate that a reduction in pro-tumorigenic/immunosuppressive Tregs is counterbalanced by the reduction of other anti-tumorigenic CD4+ T cell subsets that support CD8+ T cell anti-tumor activity." (PMID 34248938, 2021). "Furthermore, the percentage of Th17 (CD4+ IL17+) cells in the spleens of tumour-bearing mice was detected at the end of treatment." (PMID 34795289, 2021). "TAMs are enriched in the mesenchymal GBM and are associated with NF1 mutation, whereas CD8+ and CD4+ tumor-infiltrating lymphocytes (TILs) are absent from the classical and IDH-mutant proneural tumor." (PMID 34359588, 2021). "Among CD4+ T subsets, Th1 is the main subpopulation that facilitates tumor regression and a cure." (PMID 34576115, 2021). "The CD4/CD8 ratio was unaffected by age or tumor in BALB/c mice." (PMID 35008253, 2021). "Thus, while both vaccination regimens promoted trafficking of immune cells into the tumor, KV vaccination attracted the highest proportion of CTLs, CD4+ T helper cells and increased TAM-1/TAM-2 ratio thereby favorably remodeling the TME." (PMID 34465781, 2021). "Importantly, our approach has enabled the retention of tumor-specificity along with producing effector CD4+T cells which retained long-term in vitro viability." (PMID 33918403, 2021). "OX40 agonistic monoclonal antibodies in combination with the CD4+ epitope peptide vaccine showed an enhanced peptide-specific CD4+ T cell response, and a slowing of tumour progression in therapeutic models, with an increase in IFN-γ, TNF-ɑ and Granzyme B production." (PMID 34276688, 2021). "In addition, we also found that the CD3D, CD3E and LCK expression was significantly negatively related to tumor purity while positively associated with the infiltrating levels of immune cells, such as B cell, CD8 + T cell, and CD4 + T cell." (PMID 33748188, 2021). "Moreover, cytotoxic drugs abrogate Treg and MDSC activity, enhance dendritic cell activity, promote anti-tumor CD4+ T-cell phenotype and cell recognition." (PMID 34680282, 2021). "T-cell-intrinsic expression of the oxygen-sensing prolyl-hydroxylase (PHD) proteins was found to suppress anti-tumour immunity in the pre-metastatic lungs through restraining inflammatory CD4+ and CD8+ T cell responses and permitting immunosuppressive Treg differentiation." (PMID 35006432, 2021). "In addition, TGF-β secreted by tumor-evoked Bregs increased reactive-oxygen species and NO production by myeloid-derived suppressive cells, which in turn inhibited proliferation of CD4+ and CD8+ T cells, favoring metastasis." (PMID 33995344, 2021).
tumor (continued). "Alspach and colleagues showed that the presence of tumor Ag–specific cells, specifically among CD4 TILs, was necessary for tumor regression after immunotherapy by PD-1/PD-L1 axis blockade in a mouse model, suggesting that PD-1 blockade directly targets PD-1+ CD4 TILs." (PMID 33332284, 2021). "The presence of CD4+ T helper 1 (Th1) and cytotoxic CD8+ T lymphocytes can prevent tumor growth by targeting antigenic tumor cells, and high densities of activated CD8+ T cells within the tumor niche are associated with favorable prognoses in various cancers." (PMID 33463049, 2021). "The hypothesis is that the tumor mass holds CD4+ T cells close to itself to support a high level of inflammation while keeping CD8+ cytotoxic cells away, preserving tumor progression." (PMID 34070750, 2021). "The mean in situ numbers of CD3+ CD4 or CD8 TILs in MSS tumor centers tended to be lower than in MSI-H tumors, which may explain the higher APC to TIL ratio in MSS tumor suspensions from the second cohort." (PMID 34680397, 2021). "The ratio of CD4+/CD8+ CAR‐T cells also affected the anti‐tumour response in vivo." (PMID 33225580, 2021). "Stratification for PD-L1 expression revealed that tumors with positive PD-L1 expression either on tumor or immune cells (TPS/IC ≥ 1%) showed significantly increased infiltration of CD4+- and CD8+ T-cells (p = 0.002/p = 0.0003 for TPS; p < 0.0001/p < 0.0001 for IC)." (PMID 33918309, 2021). "The mechanism of CD4+ T cells was to use the cross to provide tumor antigens and costimulatory molecules to CD8+ T cells, allowing dendritic cells to activate CD8+ T cells; hence, a comprehensive analysis of the m6Acluster will help us understand the infiltration characteristics of TME cells." (PMID 34604051, 2021). "Interestingly we found that several ligands and its receptors showed positive correlation pattern: if ligands were upregulated in the tumor cells, receptors were also upregulated (upward pointing red arrow) on the lineage specific CD4+ T-cells and vice versa." (PMID 34012510, 2021). "Further, we found a decrease in the frequency of IFN-γ producing CD8+ and CD4+ T lymphocytes in the spleen as well as in the tumor draining lymph nodes (dLN) in the group of mice transferred with gefitinib-treated OT-II Th9 cells as compared to OT-II-Th9 cells." (PMID 34075041, 2021). "Importantly, A. muciniphila was associated with enhanced infiltration of immune cells in tumor sites as CCR9+CXCR3+CD4+ T cells were migrated to the site of tumor, and CD4+ T cells to CD4+FoxP3+ T cells (Tregs) ratio was elevated." (PMID 33369247, 2021). "As key regulators of tumor immune evasion, high LGALS1 expression in AML patients was associated with higher macrophages M2, monocytes infiltration, and lower naive T cells CD4, naive B cells, and resting mast cells infiltration, which remained consistent with a previous study." (PMID 35127715, 2021). "Then, NCAPG expression showed a positive correlation with tumor purity and infiltration of B cells, neutrophils, and dendritic cells, and then, no or weak associations were observed between NCAPG and infiltration of CD8+ T cells, CD4+ T cells, and macrophages." (PMID 33927744, 2021). "Recent therapeutic developments have shown that the neutralization of key pathways may have therapeutic activity in cancer patients by restoring the anti-tumor activity of CD4 T cells." (PMID 33498483, 2021). "In addition, studies also showed a reduction in Treg/MDSC cells along with tumor specific CD4 + and CD8 + T cell generation in patients when dendritic cell vaccines were combined with chemotherapeutic regimen." (PMID 34493268, 2021). "Indeed, a cytokine can have an anti-tumor role at the beginning of carcinogenesis and harbor pro-tumor activity later on with the adaptation of the tumor and the impact of intra-tumor cytokines on the activity of CD4 T lymphocytes." (PMID 33498483, 2021).